MALAT1 (metastasis associated lung adenocarcinoma transcript 1)
Diseases named in the same sentence as MALAT1 in open-access papers (continued):
Sharing a sentence is not in itself a finding about the gene and the disease.
gallbladder cancer (25 papers, 2015 to 2023). "For example, our previous study showed that lncRNA MALAT1 enhanced the proliferative capability of gallbladder cancer cells by epigenetically recruiting the enhancer of EZH2 to the ABI3BP promoter region." (PMID 37564197, 2023). "Previous studies have shown that by inhibiting ABI3BP, the long non-coding RNA, MALAT1, stimulates the proliferation of gallbladder cancer cells and prevents aging." (PMID 36744181, 2022). "For instance, MALAT1 is upregulated in MM, lung cancer, gallbladder cancer, colorectal carcinoma and HCC, whilst this lncRNA is downregulated in colorectal and glioma cancer." (PMID 33923983, 2021). "In gallbladder cancer, lncRNA MALAT1 has been documented to function as a ceRNA to negatively modulate MCL-1 expression by sponging miR-363-3p." (PMID 32760216, 2020). "MALAT1 is overexpressed in human gallbladder cancer tissues, and high levels of MALAT1 expression correlate with larger tumor size, lymphatic metastasis, and poorer overall survival." (PMID 32174966, 2020). "MALAT1 has been shown to be altered in a relevant fashion in lung, breast, prostate, and gallbladder cancers 20-22." (PMID 31777593, 2019). "For example, MALAT1 functioned as a competing endogenous RNA to regulate MCL-1 expression by sponging miR-363-3p in gallbladder cancer." (PMID 30683807, 2019). "MALAT1 functions as a competing endogenous RNA to regulate MCL-1 expression by sponging miR-363-3p in gallbladder cancer." (PMID 29212230, 2017). "To explore the potential role of MALAT1 in human gallbladder cancer, we analysed 33 pairs of human gallbladder cancer tissues and matched adjacent non‐cancerous tissues." (PMID 27420766, 2016). "In this study, qRT‐PCR analysis showed that MALAT1 expression levels were significantly increased in gallbladder cancer samples compared with adjacent normal tissues." (PMID 27420766, 2016). "In this study, MALAT1 expression was shown to be up‐regulated in gallbladder cancer tissues, and knockdown of MALAT1 inhibited cell proliferation, reduced the proportion of cells in the S phase and induced cell apoptosis." (PMID 27420766, 2016). "Knockdown of MALAT1 inhibited gallbladder cancer cell proliferation, induced cell apoptosis and decreased the tumour volume in vivo." (PMID 27420766, 2016). "It was previously reported that silencing of MALAT1 in human gallbladder cancer cells suppressed cell proliferation and invasion." (PMID 27420766, 2016). "qRT‐PCR analysis revealed that MALAT1 expression levels were significantly increased in gallbladder cancer tissue samples compared to those of adjacent normal tissues." (PMID 27420766, 2016). "A future study using a large cohort of samples from gallbladder cancer patients is needed to confirm the prognostic value of MALAT1 in GBC patients." (PMID 27420766, 2016). "Moreover, MALAT1 promotes the proliferation and metastasis of gallbladder cancer cells by activating the ERK/MAPK pathway." (PMID 31413743, 2019). "Moreover, lncRNA MALAT1 is able to promote the proliferation and metastasis of gallbladder cancer cells by activating the ERK/MAPK pathway." (PMID 29041978, 2017). "Therefore, the effect of MALAT1 on gallbladder cancer cell proliferation is due, in part, to its function as a molecular sponge of miR‐363‐3p that targets MCL‐1." (PMID 27420766, 2016). "In this study, we show that Malat1 is overexpressed in gallbladder cancer (GBC) tissue and cells." (PMID 27191262, 2016). "The MALAT1/miR‐363‐3p/MCL‐1 regulatory network may be a novel therapeutic target for gallbladder cancer." (PMID 27420766, 2016). "We transfected gallbladder cancer cell lines with two different siRNAs against MALAT1." (PMID 27420766, 2016). "To evaluate the possible role of MALAT1 in GBC, we compared MALAT1 expression in two gallbladder cancer cell lines (SGC‐996 and NOZ cells) and a human gallbladder epithelium cell line H69 and found that expression was significantly increased in the cancer lines." (PMID 27420766, 2016).
gallbladder cancer (continued). "However, the mechanism by which high Malat1 expression promotes tumorigenesis in gallbladder cancer is unknown." (PMID 27191262, 2016). "Inhibition of MALAT1 expression may be to a novel therapeutic strategy for gallbladder cancer." (PMID 27420766, 2016). "MALAT1 acts as an miRNA sponge binding to miR-1271-5p, miR-181a-5p and miR-509-5p in MM, to miR-195 in HCC or to miR-206 and miR-363-3p in gallbladder cancer." (PMID 33923983, 2021). "By functioning as a ceRNA for miR-206, MALAT1 up-regulates the expression of the oncogenic ANXA2 and KRAS, and promotes gallbladder cancer cell proliferation and invasion in vitro and tumor progression in mice." (PMID 32174966, 2020). "However, the ceRNA mechanisms for MALAT1 deregulation in gallbladder cancer have not been thoroughly elucidated." (PMID 27420766, 2016).
type 2 diabetes (24 papers, 2016 to 2025). "Logistic regression analysis revealed that NLRP3 and MALAT1 were independent risk factors for LEAD in patients with type 2 diabetes." (PMID 38439031, 2024). "The results showed that age, smoking, SBP, NLRP3, and MALAT1 were independent risk factors for LEAD in patients with type 2 diabetes (P < 0.05)." (PMID 38439031, 2024). "Metastasis-associated lung adenocarcinoma transcript 1 (MALAT1) levels were below the limit of detection in 65% and 75% of type 2 diabetes and control samples, respectively and this lncRNA was excluded from further analyses." (PMID 27874027, 2016). "The experiment concludes that aerobic exercise enhances cognitive function in type 2 diabetic mice by modulating the MALAT1/miR-382-3p/BDNF signaling pathway, facilitating neuronal growth and suppressing death." (PMID 40161268, 2025). "NEAT1 and MALAT1 were selected as vital regulators in heart failure induced by type 2 diabetes through bioinformatic analysis." (PMID 40282226, 2025). "MALAT1 is strongly associated with the progression of DN, DR and DCM, as well as it is up-regulated in peripheral blood mononuclear cells (PBMCs) from type 2 diabetes patients." (PMID 38390204, 2024). "While its link to cancer has been a primary focus in recent years, emerging studies also connect MALAT1 to chronic conditions like stroke and type 2 diabetes mellitus (T2DM)." (PMID 38543885, 2024). "In blood serum taken from Type 2 diabetes patients, increased expression in three lncRNAs, nuclear enriched abundant transcript 1 (NEAT1), metastasis-associated lung carcinoma transcript 1 (MALAT1/NEAT2), and NF-kappaB interacting lncRNA (NKILA), was observed." (PMID 36005827, 2022). "This study suggested inhibition of MALAT1 has potential for the treatment of obesity and type 2 diabetes." (PMID 26935028, 2016). "Many studies have found that lncRNAs such as MALAT1, ANRIL/CDKN2BAS, HI-LNC25, and KCNQ1OT1 are closely associated with type 2 diabetes susceptibility genes, which might affect their expression." (PMID 34941711, 2021). "Interestingly, in type 2 diabetes mices, increased MALAT1 could upregulated the expression of PI3K/AKT, INSR, and IRS-1, thereby alleviating cognitive impairment." (PMID 39502508, 2024). "Example of nomogram use: A 55-year-old male with type 2 diabetes, 10-year disease duration, peripheral neuropathy, FBG 9.5 mmol/L, 2hPG 15 mmol/L, lncRNA MALAT1 1.3, miR-199b 0.6, AGEs 150 U/mL." (PMID 41001679, 2025). "lncRNA-MALAT1 has emerged as a promising biomarker for Dr A study involving 80 patients diagnosed with type 2 diabetes and 81 healthy individuals measured the expression levels of serum miR-20b, miR-17-3p, HOTAIR, and MALAT1." (PMID 40128064, 2025). "Moreover, in a separate study by the same group, elevated MALAT1 expressions were also evident in the retinas of STZ-induced diabetic rats and db/db mice (a type II diabetes model)." (PMID 31337130, 2019). "Compared to control subjects, expression levels of lncRNAs in PBMCs from type 2 diabetes patients showed significantly (p < 0.05) increased levels of HOTAIR, MEG3, LET, MALAT1, MIAT, CDKN2BAS1/ANRIL, XIST, PANDA, GAS5, Linc-p21, ENST00000550337.1, PLUTO, and NBR2." (PMID 30139387, 2018). "Compared to control subjects, expression profiling of lncRNAs in PBMCs from type 2 diabetes patients showed significantly (p < 0.05) increased levels of HOTAIR, MEG3, LET, MALAT1, MIAT, CDKN2BAS1/ANRIL, XIST, PANDA, GAS5, Linc-p21, ENST00000550337.1, PLUTO, and NBR2." (PMID 30139387, 2018).
metastatic tumors (22 papers, 2011 to 2025). "Within this list of genes in the metastatic tumor dataset, individual genes such as TMEM45A, IGFBP1, IGFBP5, and MALAT1 appeared to be associated with a worse patient survival." (PMID 40241258, 2025). "Overall, these findings underscore MALAT1’s multifaceted role in cancer progression, suggesting its potential as a therapeutic target and biomarker for metastatic disease." (PMID 39319867, 2025). "Noteworthy in this study is that we demonstrated that mtr-miR5754 and gma-miR4995 directly target the transcripts of two lncRNAs, MALAT1, and NEAT1, which are both associated with almost all type of tumors and in particular with the metastatic tumor process." (PMID 33193626, 2020). "Another important area for further investigation is how targeting Malat1 or its downstream targets may be harnessed to limit metastatic disease." (PMID 39195572, 2024). "MALAT1 (Metastasis-Associated Lung Adenocarcinoma Transcript 1) is upregulated in clinical samples of GC and associated with depth of invasion, higher TNM stage, and prognostic marker for metastatic disease." (PMID 32987716, 2020). "For instance, targeting MALAT1 by CRISPR/Cas9 may have therapeutic potential applications in CRC, particularly in the treatment of metastatic disease." (PMID 39471147, 2024).
Stroke (22 papers, 2018 to 2026). Sudden impairment of blood flow to a part of the brain due to occlusion or rupture of an artery to the brain. "We evaluated the associations of Malat1 expression with VitD level, and IL-1β on theperipheralblood of IS patients 0-24 h after stroke onset for the first time." (PMID 38974129, 2023). "The significant associations between VitD level, Malat1 expression, IL-1β, and NIHSSwithin the first hours after stroke will provide a better and deeper understandingof the role of Malat1 expression and the protective role of VitD in strokepathogenesis." (PMID 38974129, 2023). "Malat1 is extremely abundant in brain tissues and is associated with neurological disorders, such as stroke, Alzheimer’s disease, and retinal neurodegeneration." (PMID 36482889, 2022). "Metastasis-associated lung adenocarcinoma transcript 1 (MALAT1) participates in the occurrence and development of cardiovascular and cerebrovascular diseases such as stroke and coronary heart disease by regulating inflammatory reactions, programmed cell death, and other pathological processes." (PMID 35392816, 2022). "MALAT1 was proven to act as a competing endogenous RNA (ceRNA) to facilitate the berberine-mediated inhibition of HMGB1 by sponging miR-181c-5p in post-stroke inflammation." (PMID 39859155, 2025). "They found that 21 co-expressed DE genes and two co-expressed lncRNAs (MALAT1 and GABPB1-AS1) are associated with HF-related stroke." (PMID 40283676, 2025). "Metastasis-associated lung adenocarcinoma transcript 1 (MALAT1) is a long, non-coding RNA that protects the BBB after stroke." (PMID 40077636, 2025). "Transcriptomic analyses of stroke tissues have identified several lncRNA–miRNA–mRNA axes—such as MALAT1–miR-26b–ULK2—that potentially regulate autophagy and inflammation across diverse cell types, including microglia." (PMID 41007413, 2025). "The MALAT1/miR-181c-5p/HMGB1 axis has been identified as a novel key pathway in stroke inflammation." (PMID 39859155, 2025). "The evaluation of stroke severity in IS patients revealed that the Malat1 expressionsignificantly was lower (2.7±0.51 vs 5±1.3, P=0.001) in patients with high NIHSSscore (>7),while IL-1β was higher in patients with NIHSS 0-6 (65.3±7.7 vs 35.1±2.9, P=0.000)." (PMID 38974129, 2023). "A previous study confirmed that MALAT1 Up-regulator polydatin protects brain microvascular integrity and ameliorates stroke through C/EBPβ/MALAT1/CREB/PGC-1α/PPARγ pathway." (PMID 35902882, 2022). "LncRNAs ANRIL (non-coding antisense RNA in the INK4 locus), MALAT1 (metastasis-associated lung adenocarcinoma transcript 1), MEG3 (maternally expressed 3), TUG1 (taurine upregulated 1) and ANRIL expression were significantly increased in stroke models." (PMID 35741740, 2022). "To date, lncRNA-H19, HOTAIR, CCAT1, and MALAT1 have been widely considered to be closely related to the occurrence and development of stroke." (PMID 31934270, 2019). "Other studies have observed MALAT1 as protective in other internal injuries such as ischemia-reperfusion injury of the lung after transplant and in hypoxic and ischemic brain injury after strokes." (PMID 40331955, 2025). "in 2021 also reported the downregulation of Malat1 in IS patients with a negativeassociation with stroke severity Thesoluble glycoproteins that are produced by microglia, astrocytes, endothelial cells,and neurons in response to damaged brain tissue are cytokines." (PMID 38974129, 2023). "Thisresult may reinforce the anti-inflammatory role of lncRNA Malat1 after stroke whichhas beenreported by previous studies." (PMID 38974129, 2023). "In vivo experiments confirmed that lncRNA MALAT1 was involved in the regulation of stroke damage." (PMID 32138732, 2020). "Similarly, MALAT1 can also sponge miR-30a, releasing translational inhibition on Beclin-1, which promotes autophagosome formation and reduces neuronal apoptosis following stroke." (PMID 41007413, 2025).
Stroke (continued). "As an example, the lncRNA Malat1 may play a protective role in ischemic stroke through the inhibition of proapoptotic proteins and proinflammatory cytokines, suggesting that lncRNAs may offer novel targets to reduce stroke-related brain damage." (PMID 38003403, 2023). "It is speculated that lncRNA MALAT1 promotes angiogenesis to alleviate nerve damage in stroke." (PMID 35053294, 2022). "Specific blockage of MALAT1 is expected to be a potential therapeutic target for the protection of neuronal function in stroke patients, which may contribute to the further development of therapeutics against stroke and provide a new opportunity to improve the prognosis of patients." (PMID 33750458, 2021). "Accumulating data from basic and clinical studies have disclosed that lnc-MALAT1 could protect ischemia-induced brain microvascular endothelial cells (BMECs), implying that lnc-MALAT1 might be involved in cerebrovascular pathologies in stroke." (PMID 33111743, 2020). "Furthermore, MALAT1 showed higher expressionin patients with previous history of stroke." (PMID 31188931, 2019). "It is particularly noteworthy that LncRNA KCNQ1OT1, MALAT1, MIR17HG, and RMST are upregulated in hS3-treated healthy neuronal cultures, as these lncRNAs are known to be highly upregulated in stroke and inflammatory diseases." (PMID 41602576, 2026). "Patients with an NIHSS score>7 showed a significantly higher level of IL-1β andlowerexpression of Malat1 relative to other patients who had an NIHSS score<6 while wecouldn’tdetect a significant negative correlation between stroke severity and VitD level." (PMID 38974129, 2023). "A well-studied lncRNA, MALAT1, was reported to contribute to protecting the BBB after stroke." (PMID 34198485, 2021). "MALAT1 and ANRIL were previously demonstrated to serve as protective or detrimental predicting factors for stroke under certain circumstances." (PMID 35096003, 2021). "MALAT1/miR-181c-5p/HMGB1 axis may be a key pathway of antiinflammation induced by berberine, highlighting its potential as a therapeutic targets for modulating inflammation and improving stroke outcomes." (PMID 39859155, 2025). "VitDlevel showed a positive Pearson correlation with Malat1 (r=0.28, P=0.023) and anegative correlation with IL-1β (r=-0.29, P=0.018) while it could not detect asignificantly negative correlation with stroke severity." (PMID 38974129, 2023).
triple-negative breast carcinoma (22 papers, 2016 to 2025). An invasive breast carcinoma which is negative for expression of estrogen receptor (ER), progesterone receptor (PR), and human epidermal growth factor receptor 2 (HER2). "Targeting MALAT1 in association with PARPi: in triple negative breast cancer, lncRNAs can be used to cluster the patients in subgroups, while five transcripts of the MALAT1 gene are specifically upregulated in resistant patients and are involved in resistance to chemotherapy." (PMID 39280246, 2024). "Correlational studies have previously demonstrated that solely the processed form of MALAT1 could associate with higher mortality in triple-negative breast cancer whereas other regions (such as the mascRNA) do not correlate with tumorigenesis." (PMID 31382922, 2019). "A case in point is seen with JAG1, which stimulates angiogenesis in triple-negative breast cancer by facilitating the release of the exosomal lncRNA MALAT1." (PMID 38965575, 2024). "The highest level of MALAT1 was observed in metastatic triple-negative breast cancer and trastuzumab-resistant HER2 (human epidermal growth factor receptor 2) overexpressing (HER2+) cells." (PMID 32708561, 2020). "In this paper, we aimed to discuss how MALAT1 is connected with and affects proliferation and invasion abilities of cells in Her-2 positive and triple-negative breast cancers (TNBC)." (PMID 29416769, 2018). "In this study, we demonstrated the critical roles of KDM5B and its downstream target MALAT1 in triple negative breast cancer metastatic phenotype and clinical prognosis, based on the following observations: (i)." (PMID 26917489, 2016). "Future experiments aimed at evaluating whether overexpression of MALAT1 in cell models of basal-like triple-negative breast cancer reverses the stabilization of SOX9 mRNA could help assess the role of MALAT1-HuR in EMT regulation." (PMID 38254873, 2024). "MALAT-1 has been shown to relieve the inhibitory effect of miR-34a on the expression of PD-L1 and B7-H4 on the surface immune checkpoints of triple-negative breast cancer cells, which can induce the apoptosis of NKs and cytotoxic T cells in the tumor microenvironment." (PMID 37637063, 2023). "In addition, some studies indicated that MALAT1 promoted proliferation and invasion via targeting miR-129-5p in triple-negative breast cancer." (PMID 30683807, 2019). "To explore whether MALAT1 regulates proliferation and invasion abilities of triple-negative breast cancer cells through XBP1-HIF1α, we firstly detected the expressions of XBP1 and HIF1α in MDA-MB-231 by qRT-PCR after the knockdown of MALAT1." (PMID 29416769, 2018). "In addition, the ectopic expression of KDM5B and its downstream effector gene, MALAT1, inversely corrected with that of hsa-miR-448 in the triple negative breast cancer cells." (PMID 26917489, 2016). "Another study suggests that MALAT1 regulates the miR-1/Slug axis through a reciprocal negative regulation in triple-negative breast cancer." (PMID 32708601, 2020). "Moreover, in triple-negative breast cancer, lncRNA HOTAIR and MALAT1 play a synergistic role in promoting M2-like polarization of macrophages, and the simultaneous knockout of HOTAIR and MALAT1 can increase the expression levels of M1-like macrophage markers CD80 and MSLN." (PMID 37637063, 2023).